TPO (thyroid peroxidase)
Diseases named in the same sentence as TPO in open-access papers (continued):
Sharing a sentence is not in itself a finding about the gene and the disease.
Hashimoto thyroiditis (continued). "This would be similar to the pathologic mechanism through which the autoantibodies to thyroglobulin, thyroid peroxidase and/or the thyroid-stimulating hormone receptor function in Hashimoto's thyroiditis." (PMID 21521495, 2011). "Hashimoto's thyroiditis is characterised by glandular hypo-function, destruction of thyroid cells and production of an immunoglobulin G (IgG) response directed against TPO." (PMID 20145622, 2010). "Patients with Hashimoto's thyroiditis had been treated with T4 for a mean of 43 months when entering the study and were euthyroid and with positive anti-TPO (1452 IU/L (785-2686)." (PMID 20807449, 2010). "Elevated levels of anti-TPO are seen in more than 90% cases of Hashimoto thyroiditis and about 75% of Graves' disease cases." (PMID 16526964, 2006). "It is also known as lymphocytic thyroiditis, which is characterized by a diffuse lymphocytic infiltration and elevated levels of antibodies, such as those against thyroglobulin (anti-Tg) and thyroid peroxidase (anti-TPO)." (PMID 41226614, 2025). "Furthermore, our diagnostic approach to autoimmune POI was relatively broad, as it included Hashimoto’s thyroiditis with anti-TPO positivity." (PMID 40647723, 2025). "Among the key immunological factors involved in Hashimoto’s thyroiditis, anti-thyroid peroxidase (Anti-TPO) and anti-thyroglobulin (Anti-Tg) antibodies play a central role, being closely associated with ovarian inflammation and an increased risk of miscarriage." (PMID 40564214, 2025). "Moreover, in subjects with overt or SH, the evaluation of TPO-Ab and TG-Ab titers can differentiate children with autoimmune or non-autoimmune hypothyroidism." (PMID 41585793, 2025). "Hashimoto’s thyroiditis is immune-mediated, characterized by the production of anti-thyroid peroxidase (ATPO) and anti-thyroglobulin (A-Tg) antibodies, which may influence ovarian function and embryo implantation." (PMID 40564214, 2025). "While on the opposite side, in Hashimoto's thyroiditis antibodies against thyroid peroxidase (TPO) and thyroglobulin (TG) - antithyroid peroxidase antibodies (TPOAb), and antithyroglobulin antibodies (TGAb) - leading to destruction of the thyroid tissue and resulting in a hypothyroid state." (PMID 40524917, 2025). "Pro-inflammatory arachidonic acid (AA) derivatives may play a vital role in the development of Hashimoto’s Thyroiditis (HT) and the production of anti-thyroid peroxidase antibodies (ATPO) and anti-thyroglobulin antibodies (ATG)." (PMID 41439954, 2025). "Our patient had elevated TSH with low normal T4, positive anti-TPO, positive anti-TG, and ultrasound neck revealing heterogenous, diffusely enlarged thyroid gland with linear echogenic septations, thereby meeting the criteria for Hashimoto’s thyroiditis." (PMID 39132944, 2024). "The results showed significantly decreased levels of free triiodothyronine (FT3) and free thyroxine (FT4) and increased levels of TSH and thyroid peroxidase (TPO) antibodies in patients with COVID-19 six months after the initial infection suggesting autoimmune hypothyroidism." (PMID 39544551, 2024). "Hashimoto's thyroiditis (HT) is an autoimmune disease characterized by the production of thyroid autoantibodies against thyroid peroxidase (TPO) and thyroglobulin (Tg) that attack thyroid cells by cell‐ and antibody‐mediated immune processes and cause progressive fibrosis." (PMID 38370054, 2024). "Also, 18 patients had autoimmune hypothyroidism with a high anti-TPO antibody level but a normal anti-Tg antibody level." (PMID 38807724, 2024). "High titers ofanti-TPO antibodies are found in 95% of patients with Hashimoto's thyroiditis." (PMID 39224552, 2024). "Thyroid peroxidase antibody (TPO-Ab) and thyroglobulin antibody (TG-Ab) are autoantibodies targeting thyroid antigens and are considered important clinical markers for Hashimoto’s thyroiditis (HT), with positivity rates of approximately 75% and 90% in HT patients, respectively." (PMID 39363900, 2024).
Hashimoto thyroiditis (continued). "Increased antibodies to TPO suggest that a patient may have an autoimmune disease called Hashimoto’s disease." (PMID 39650960, 2024). "Hashimoto thyroiditis was diagnosed with positive anti‐TPO antibodies." (PMID 40626246, 2024). "Resolvin D1 may have the greatest potential to positively influence inflammation in inflammatory thyroid disease, Hashimoto’s thyroiditis, as it lowers both anti-TPO and anti-TG antibody levels." (PMID 39519244, 2024). "Among the ten cases with Hashimoto disease, the diagnosis was established based on increased levels of anti-TPO antibodies in eight children, while the other two had increased levels of both anti-TPO and anti-Tg antibodies." (PMID 39728741, 2024). "Other factors such as sex (p = 0.174), BMI (p = 0.939), Tg (p = 0.128), anti-Tg (p = 0.270), anti-TPO (p = 0.112), Graves’ disease (p = 0.369), Hashimoto’s disease (p = 0.432), and the size of the dominant nodule (p = 0.285) did not significantly affect the discrepancy between US-TV and IO-TV." (PMID 37892758, 2023). "Distribution of sex, age, Hashimoto thyroiditis, TPO-Ab, and TG-Ab levels." (PMID 37033256, 2023). "Iodine intake may be a potential confounder in our results; moreover, anti-TPO antibodies are significant in confirming the onset of chronic thyroiditis." (PMID 38137904, 2023). "In individuals with Hashimoto’s thyroiditis, the production of anti-thyroid peroxidase antibodies (anti-TPO antibodies) and anti-thyroglobulin antibodies can lead to attacks on thyroid tissue, affecting thyroid hormone synthesis and causing inflammation and damage." (PMID 37876541, 2023). "The proinflammatory cytokine concentrations of IL-8, IL-10, IL-1B, and TNF-α were found to be significantly increased in patients with Hashimoto’s disease, who have anti-thyroid peroxidase antibodies and/or anti-thyroglobulin antibodies as compared to age- and sex-matched controls." (PMID 37241088, 2023). "Finally, we found that anti-TPO is more sensitive and specific in detecting cases of Hashimoto thyroiditis." (PMID 37377479, 2023). "Moreover, Hashimoto's thyroiditis inactivates thyroid peroxidase and is recognized as an antigen, leading to intrathyroidal lymphocytic infiltration and the formation of TPO-Abs." (PMID 37153231, 2023). "Hashimoto’s thyroiditis (HT), also known as chronic lymphocytic thyroiditis, is an autoimmune disorder clinically characterized by signs and symptoms of hypothyroidism and elevated levels of antithyroid peroxidase (TPO) antibodies in the serum of patients affected." (PMID 35794773, 2023). "However, a humoral component resembling classic Hashimoto’s disease is also assumed to exist, based on a higher prevalence of irT in patients with pre-existing anti-thyroid peroxidase (TPO) antibodies." (PMID 35205622, 2022). "She had Hashimoto thyroiditis as well with positive anti-TPO antibody (213 IU/ml)." (PMID 35958611, 2022). "The principal autoantigens in Hashimoto's disease are thyroid peroxidase (TPO) and thyroglobulin (Tg), although these antibodies (anti-thyroid peroxidase (anti-TPO) antibody and anti-thyroglobulin (anti-Tg) antibody) are also found in 70% of Graves' disease patients." (PMID 35911325, 2022). "It should also be remembered that anti-TPO antibodies form immune complexes that activate the complement and T cells, thus contributing to an increase in the level of pro-inflammatory cytokines in patients with Hashimoto’s disease." (PMID 33808030, 2021). "However, Given TPO and TG antibodies are related with Hashimoto’s thyroiditis, and their expression suggest an abnormal autoimmunity." (PMID 31840740, 2020). "Thyrotropin receptor antibodies (TRAb) and/or thyroid-stimulating antibody (TSAb) are usually used for diagnosis of Basedow’s disease, and thyroid peroxidase antibodies (TPOAb) and/or thyroglobulin antibodies (TgAb) are for diagnosis of Hashimoto’s thyroiditis." (PMID 32758269, 2020).
Hashimoto thyroiditis (continued). "Hashimoto’s thyroiditis (HT) is identified by lymphocytes infiltration in the thyroid gland which leads to the destruction of thyroid follicles, and the production of autoantibodies against thyroid peroxidase (TPO, 90–95%) and thyroglobulin (TG, 20–50%)." (PMID 33114469, 2020). "Patients presenting as multinodular Hashimoto's thyroiditis have low prevalence of elevated anti-TPO-Ab than diffuse HT which suggests that multinodular form of Hashimoto's thyroiditis is a unique clinical entity with etiopathogenesis that is at variance with the diffuse form." (PMID 31428301, 2019). "Anti-thyroperoxidase (TPO) AAb were positively associated with FM in several studies, even in patients without Hashimoto’s thyroiditis and hypothyroidism." (PMID 31635218, 2019). "Furthermore, in the current study, Hashimoto’s thyroiditis patients with high titers of anti-TPO antibody were more likely to exhibit diffusely swollen thyroids with a heterogeneous pattern on US." (PMID 30349584, 2018). "In this study, we evaluated patients with Hashimoto’s thyroiditis, which was diagnosed based on the elevation of either anti-TPO titer or anti-Tg titer; Hashimoto’s thyroiditis patients with high titers of anti-thyroid antibodies were likely to exhibit intense diffuse FDG uptake in the thyroid." (PMID 30349584, 2018). "Moreover, anti-TPO also has superiority over anti-Tg for detecting AITDs such as Graves' disease and Hashimoto thyroiditis." (PMID 30515422, 2018). "Approximately 85–90% of patients with chronic thyroiditis have anti-TPO antibodies; therefore, these antibodies are considered to be the hallmark of autoimmune thyroid disease (ATD), particularly, Hashimoto’s thyroiditis, postpartum thyroiditis, and Grave’s disease." (PMID 29915578, 2018). "Hashimoto's thyroiditis (HT) is an autoimmune disease that is characterized by the infiltration of mononuclear cells in the thyroid, together with the production of autoantibodies against thyroglobulin and thyroid peroxidase (TPO)." (PMID 29593681, 2018). "The major autoantigens in Hashimoto’s disease are thyroid peroxidase (TPO) and thyroglobulin (Tg)." (PMID 26062519, 2016). "In addition, a higher prevalence of TPO Abs and autoimmune hypothyroidism has been reported in patients with bipolar affective disorder, irrespective of the usage of lithium." (PMID 27092550, 2016). "One child was diagnosed as having Graves' disease based on a positive result for thyroid stimulating antibody and 3 children were diagnosed as having Hashimoto's thyroiditis based on positive results of anti-thyroglobulin antibody and anti-thyroid peroxidase antibody." (PMID 25762224, 2015). "It is interesting to note that there is also an association between another allergic disease (chronic urticaria) and Hashimoto's thyroiditis, as TPO and/or Tg autoantibodies were found more frequently in patients with chronic urticaria and angioedema compared to healthy controls." (PMID 25140177, 2014). "The prevalence (97.1%) of increased anti-Neu5Gc antibodies in Hashimoto's disease equals and even exceeds the prevalence of anti-TPO antibodies (80% in the present study, 90% according to the literature) which is the most characteristic autoantibody associated with the disease." (PMID 25003133, 2014). "Although TPO antibodies (TPOAbs) are a useful clinical marker for the detection of early AITD, it remains controversial if these antibodies play a causative role in the pathogenesis of Hashimoto's thyroiditis." (PMID 24586183, 2014). "TPO Ab is more specific and sensitive than TG Ab in the diagnosis of autoimmune hypothyroidism." (PMID 23878745, 2013). "Moreover, chronic thyroiditis is characterized by the presence of thyroid antibodies; antibodies against thyroperoxidase (TPO) are the most specific ones." (PMID 23259526, 2012).
Hashimoto thyroiditis (continued). "Serum thyroid peroxidase antibodies were considered high whether their concentrations were higher than 40 UI/ml, and they were high in 100 percent of patients with Hashimoto's thyroiditis." (PMID 20509904, 2010). "Moreover, multiple linear regression analysis has demonstrated that the presence of Hashimoto thyroiditis is significantly associated with serum catestatin levels, independent of age, BMI, systolic blood pressure, AGEs, hsCRP, TSH and anti-TPO serum concentrations (β 1.819, SE 0.830, p = 0.030)." (PMID 40001472, 2025). "Additionally, a significant decrease in TPO-Abs was observed in patients with Hashimoto’s disease." (PMID 38635065, 2024). "Hashimoto’s thyroiditis (HT), also known as chronic lymphocytic thyroiditis, is a common autoimmune disorder characterized by widespread thyroid enlargement and the presence of high levels of thyroid peroxidase antibodies (TPOAb) and thyroglobulin antibodies (TgAb) in the serum." (PMID 39403393, 2024). "Hashimoto’s thyroiditis (HT) is an autoimmune disruption manifested by immune cell infiltration in thyroid tissue and the production of antibodies against thyroid-specific antigens, such as the thyroid peroxidase antibody (TPOAb) and thyroglobulin antibody (TGAb)." (PMID 38137348, 2023). "Finally, anti-TPO is a sensitive marker for detecting Hashimoto thyroiditis, which could be used for future referencing of newly diagnosed cases." (PMID 37377479, 2023). "Based on those hypotheses, several studies have provided selenium supplementation for patients with Hashimoto’s thyroiditis and have reported decreases in thyroid peroxidase antibody (anti-TPO Ab) titers and normalization of the thyroid parenchyma on ultrasonography." (PMID 37060084, 2023). "Hashimoto’s thyroiditis (HT) is a common endocrine disease marked by the diffuse infiltration of immune cells in the thyroid gland, which generate a mass of autoantibodies directed against thyroid-specific antigens, including thyroglobulin (TG) and thyroperoxidase (TPO)." (PMID 36874364, 2023). "Therefore, this elevation of TPO-Abs may be because the females in the study group were autoimmune hypothyroid patients." (PMID 37153231, 2023). "Anti-thyroid peroxidase (anti-TPO) Ab was significantly more common in vitiligo patients, especially in young women, as this antibody is a relatively sensitive and specific marker of autoimmune thyroid disorders, including Hashimoto's thyroiditis (HT) and Graves' disease." (PMID 36694854, 2023). "Hashimoto’s thyroiditis (HT) is a prevalent autoimmune disorder that primarily impacts the thyroid and is characterized by intrathyroidal monocyte infiltration and elevated serum levels of autoantibodies specific for thyroid peroxidase (TPO-Ab) and thyroglobulin (Tg-Ab)." (PMID 35468730, 2022). "Second, because histopathologic examination was not performed, it was uncertain whether the anti-TPO positivity resulted from an underlying chronic thyroiditis or was an atypical presentation of SAT." (PMID 35551678, 2022). "The initial concentration of anti-TPO was lower compared to other studies that also included patients with newly diagnosed and previously untreated Hashimoto’s disease, which may have been partly reflected in the higher levels of CRP in studies by other authors." (PMID 35889825, 2022). "However, the anti-TPO antibody is phenotypically associated with Hashimoto’s thyroiditis, but not autonomic neuropathy." (PMID 36614874, 2022). "As the most common organ-specific autoimmune disorder, Hashimoto’s thyroiditis (HT) is characterized by infiltration of the thyroid gland by inflammatory cells and production of autoantibodies to thyroid-specific antigens such as thyroglobulin (Tg) and thyroid peroxidase (TPO)." (PMID 26761929, 2016).
Hashimoto thyroiditis (continued). "Serum of a Hashimoto thyroiditis patient served as positive control, showing both granular staining in the cytoplasm of the follicle epithelium (white arrowheads) and coarse staining in the colloid of follicles (white asterisk), which represented anti-TPO and anti-TG seropositivity, respectively." (PMID 22126669, 2011). "The patient developed Hashimoto's thyroiditis at age 18 with elevated TSH, low normal free T4, and positive thyroid peroxidase (TPO) antibodies, and levothyroxine therapy was initiated." (PMID 40027259, 2025). "Anti-thyroid peroxidase (anti-TPO) and anti-thyroglobulin (anti-Tg) antibodies are common in Hashimoto’s thyroiditis." (PMID 41157173, 2025). "Elevated anti-thyroid peroxidase antibodies (TPO-Ab), indicative of Hashimoto’s thyroiditis, are frequently observed in patients with RNF213-related ICASO and MMD." (PMID 40869987, 2025). "In a six-year follow-up study of the same population, Wu reported that an increased level of thyroid peroxidase (TPO) antibodies and a higher incidence of Hashimoto’s disease occurred in the group with low selenium intake." (PMID 38714999, 2024). "AIT, also known as Hashimoto’s thyroiditis (HT) or chronic lymphocytic thyroiditis, is characterized by excessive production of TGA and TPO and infiltration of lymphocytes into thyroid tissue." (PMID 39764244, 2024). "Heterogeneity was very high (I2 > 75%) in the Hashimoto’s thyroiditis group, moderately high (I2 = 50-75%) in the age, TSH, anti-TPO and anti-Tg groups, and low (I2 < 50%) for female sex, TSH ≥ 2 mIU/L and side of hemithyroidectomy groups." (PMID 38972987, 2024). "Antibodies against thyroid peroxidase (TPO) and thyroglobulin (TG) known as anti-microsomal antibodies have been detected in Hashimoto’s thyroiditis, Graves’ disease." (PMID 37907956, 2023). "The patients of Hashimotos thyroiditis had raised levels of serum TSH and Anti-TPO antibodies at the time of diagnosis." (PMID 36741403, 2022). "Hashimoto’s disease could be considered a T helper 1 disease in which pro-inflammatory cytokines play a crucial role, and there is a connection between the level of anti TPO antibodies and pro-inflammatory cytokines that appears at higher concentrations in individuals with insulin resistance." (PMID 35807200, 2022). "This study aimed to investigate the prognostic value of chronic lymphocytic thyroiditis (CLT) and preoperative thyroid peroxidase antibody (TPOAb) in PTC patients." (PMID 35615152, 2022). "Two patients (BSS5 and BSS7) who were diagnosed with Hashimoto’s thyroiditis were positive for anti- TG-Ab and one of them (BSS7) for TPO-Ab." (PMID 31924231, 2020). "Graves’ disease and Hashimoto’s thyroiditis are representative AITD, and TRAb is the autoantibody for Graves’ disease, while the anti-thyroid peroxidase (TPO) antibody and anti-thyroglobulin antibody are autoantibodies for Hashimoto’s thyroiditis." (PMID 33260824, 2020). "Green coffee, green tea, cumin, and mustard contain potentially bioaccessible TPO activators that also act as effective LOX inhibitors, which indicate their potentially health-promoting effects for people suffering from Hashimoto’s disease." (PMID 31671724, 2019). "However, we could not explain the exact reason for different impact of smoking on TPO Ab according to gender, we postulate there are possibility the impact of smoking on female is less small comparing that on men, because Hashimoto’s thyroiditis occurs predominatly in females than in males." (PMID 30862792, 2019). "Hashimoto’s disease is usually diagnosed by high TSH and elevated antithyroid peroxidase (anti-TPO) and/or anti thyroglobin (anti-TG) antibodies." (PMID 27200380, 2016). "Thyroid peroxidase (TPO) is the major autoantigen and TPO antibodies (TPO-Abs) are present in almost all patients with autoimmune hypothyroidism and precede the clinical phase of autoimmune hypothyroidism by many years." (PMID 27092550, 2016).